CD96 (CD96 molecule)
Diseases named in the same sentence as CD96 in open-access papers (continued):
Sharing a sentence is not in itself a finding about the gene and the disease.
chronic obstructive pulmonary disease (1 paper, 2022). A chronic and progressive lung disorder characterized by the loss of elasticity of the bronchial tree and the air sacs, destruction of the air sacs wall, thickening of the bronchial wall, and mucous accumulation in the bronchial tree. "The study shows that the expression levels of NK cell surface receptors were abnormal in chronic obstructive pulmonary disease (COPD) patients compared with healthy controls, especially inhibitory receptors CD96." (PMID 35866671, 2022).
clear cell carcinoma (1 paper, 2021). "While these data are in line with a study showing anti-tumor activity of anti-CD96 mAbs against a human clear cell carcinoma cell line xenotransplanted in SCID beige mice, they are opposed by a recent report indicating that CD96 crosslinking activates mouse and human CD8+ T cells." (PMID 34503073, 2021).
coronary artery disease (1 paper, 2024). "A recent study found that CD155 is highly expressed on macrophages in patients with coronary artery disease (CAD), delivering negative signals to CD4+ T cells expressing CD96 and/or TIGIT receptors." (PMID 39926714, 2024).
Crohn disease (1 paper, 2022). A gastrointestinal disorder characterized by chronic inflammation involving all layers of the intestinal wall, noncaseating granulomas affecting the intestinal wall and regional lymph nodes, and transmural fibrosis. "A genome-wide significant association between the CD96 locus and the production of antibodies to anti-TNF treatment was found in Crohn's disease (CD)." (PMID 35769669, 2022).
endometrial carcinoma (1 paper, 2025). A malignant tumor arising from the epithelium that lines the cavity of the uterine body. "Through our analysis of the TCGA dataset, we discovered that in Uterine Corpus Endometrial Carcinoma (UCEC) samples, the expression level of SLC2A1 was negatively correlated with the expression levels of CD96, CTLA-4, and PDCD-1." (PMID 40746529, 2025).
metastatic tumors (1 paper, 2022). "We also show that expression of CD96, a co-stimulatory marker in T cells, was elevated in metastatic tumors from women." (PMID 36387163, 2022).
myeloid neoplasm (1 paper, 2018). Proliferation of myeloid cells originating from a primitive stem cell. "Given the potential for CD96-targeted mAb therapy in myeloid neoplasms, especially the capability to specifically target AML LSCs, it is surprising that no clinical trials of anti-CD96 therapy have yet been reported." (PMID 29868474, 2018).
neuroblastoma (1 paper, 2024). Neuroblastoma (NB) is the most common solid, extracranial childhood tumor. "We confirmed significantly increased CD96 expression, and a trend of increased TIGIT expression in neuroblastoma-infiltrating NK cells by flow cytometry." (PMID 38181797, 2024).
skin tumors (1 paper, 2020). "Interestingly, we found Pd‐1 and its ligands Pd‐l1 and Pd‐l2 as well as Tigit, Tim3, and Cd226 to be significantly upregulated in skin tumors, whereas Lag3 and Cd96 were not significantly changed compared to control skin." (PMID 32615027, 2020).
spontaneous abortion (1 paper, 2023). Expulsion of the product of FERTILIZATION before completing the term of GESTATION and without deliberate interference. "To clarify CD96 and CD155 expression at the maternal–foetal interface, we performed immunofluorescence staining of the normal endometrium (NE) tissues and decidua tissues from normal pregnancy (NP) women and spontaneous abortion (SA) women." (PMID 37760110, 2023).
T-cell lymphoma (1 paper, 2023). "It is important to note that there are currently no data on CD96 expression in T-cell lymphoma, which opens up new avenues for investigation of CD96 in in relation to this malignancy." (PMID 36674817, 2023).
tongue squamous cell carcinoma (1 paper, 2021). A squamous cell carcinoma that arises from the tongue. "A previous study has developed a 16-gene prognostic signature that can predict the prognosis of patients with tongue squamous cell carcinoma, including CD96, HNF1B, and SMG1." (PMID 34322156, 2021).
type 1 diabetes (1 paper, 2020). "Enhancement of CD8+ T cell pathogenicity by dual TIGIT and CD96 blockade could therefore be expected to augment type 1 diabetes development in NOD mice." (PMID 33013915, 2020).
vitiligo (1 paper, 2025). Generalized well circumscribed patches of leukoderma that are generally distributed over symmetric body locations and is due to autoimmune destruction of melanocytes. "Conversely, pathways associated with tissue homeostasis and regeneration were enriched in HC, including CD96 and IGFBP, reflecting the disrupted balance between inflammation and repair in vitiligo skin." (PMID 41498037, 2025).
tumor (178 papers, 2012 to 2026). "CD96 is also expressed on tumor cells and is associated with chemotherapy resistance and poor prognosis." (PMID 39156900, 2024). "The percentage of cancer cell‐intrinsic CD96 was inversely associated with the percentage of apoptotic tumor cells in patients with BC who underwent neoadjuvant therapy." (PMID 36581470, 2023). "It was tested if histomorphological parameters, including T-, N-, L-, Pn-status, and tumor grading, are associated with CD96 expression in the tissue and blood samples of OSCC patients." (PMID 37046787, 2023). "The deficiency of NK cells-derived CD96 checkpoint was showed increased tumor resistance in chemically produced tumor models of mice which were also dependent on NK and IFN-γ." (PMID 36109471, 2023). "This indicates that a high expression of the immunosuppressive checkpoint ligand PD-L1, which is mainly found on APCs and tumor cells, is associated with an increased CD96 expression on local T and NK cell populations." (PMID 37046787, 2023). "Multiple immunofluorescent staining of CD96, ALDH1, and CK demonstrated that CD96 was co‐expressed in most ALDH1+CK+ cells, and the percentages of CD96+ were significantly associated with ALDH1+ percentages in CK+ tumor cells from clinical BC samples." (PMID 36581470, 2023). "Antibody-mediated blockade and genetic deficiency of CD96 was shown to enhance CTL activities in several mouse tumor models." (PMID 35406483, 2022). "On the contrary, cross-linking of CD96 was demonstrated to promote CTL activation, and CD96-deficient CTLs were demonstrated to exert impaired anti-tumor activity." (PMID 35406483, 2022). "The expression of PD-L1, CTLA4, TIM-3, and CD96 was significantly higher in high-risk populations than in low-risk populations, indicating that GILncSig expression was related to a high tumor immune resistance." (PMID 35571034, 2022). "An example for these paired receptors pose the Ig superfamily receptors DNAM-1, TIGIT, CD112R/PVRIG and CD96/TACTILE which bind to tumor associated ligands of the Nectin or Nectin-like (Necl) family." (PMID 35371071, 2022). "In chemical-induced tumor models, mice deficient in CD96 displayed more resistance to tumor growth in both an NK and IFN-γ –dependent manner." (PMID 31552017, 2019). "We have demonstrated that platelets robustly suppress surface expression of CD226 and CD96 on the NK cell surface and their associated ligands on the tumour cell to further enhance NK cell suppression." (PMID 30908480, 2019). "CD96 deficient animals had a better control of tumor growth compared to wild-type mice." (PMID 37046787, 2023). "Notably, both TIGIT and CD96 are significantly up-regulated on NK and T cells that are chronically stimulated by tumor cells, and their expression is a hallmark of poor prognosis and resistance to chemotherapy." (PMID 37629138, 2023). "To explore whether CD96 is involved in the process of immune infiltration in pan-cancer, we first evaluated the association between CD96 expression and tumor purity." (PMID 33680972, 2021). "Moreover, CD96-deficient mice showed decreased experimental tumor metastasis, suggesting that CD96 and DNAM-1 oppose each other in tumor immunity." (PMID 27049654, 2016). "It is involved with a variety of cancer-associated functions, including the intrinsic activity of tumor cells that regulate proliferation, adhesion, and migration, as well as the ability to influence the immune response by binding to the immunomodulatory receptors dNaM-1, CD96, and TIGIT." (PMID 35768666, 2022). "Moreover, the reduction of CD226+ and CD96+ NK cells is correlate with tumor histological grade and lymph node metastasis, and the decreased percentages of CD226+ and CD96+ NK cells could cause tumor immune escape in PC patients." (PMID 33128857, 2020). "Up-regulation of CD96 expression in tumor-infiltrating NK cells leads to NK cell dysfunction, which is associated with poor clinical prognosis." (PMID 40463500, 2025).
tumor (continued). "In terms of specific communication signals, tumor-associated ductal cells increase the output of signals such as ALCAM and OCLN and the input of signals such as CD96 and CD6." (PMID 40688078, 2025). "Research indicates that co-expression and association of CD96 and CD160 with CD318 influence the regulation and activation of CD8+ T cells and NK cells, thereby affecting cytotoxic responses and anti-tumor immunity." (PMID 40725832, 2025). "The results showed that the removal of PDCD1 and CD96 significantly contributes to the suppression of tumor growth, leading to complete remission." (PMID 41369346, 2025). "CD155 interacts with both the costimulatory receptor CD226 and the inhibitory receptor CD96, influencing immune responses ranging from enhanced NK cell adhesion and cytotoxicity to tumor immune evasion and metastasis." (PMID 40362354, 2025). "In studies, TIGIT and CD96 knockout has led to an increase in the cytotoxicity of NK cells and a suppression of tumor metastasis." (PMID 41369346, 2025). "In GBM, CD96 co-expressed with PD-1 on CD8+ T cells indirectly promote tumor growth via enhanced IFN-γ secretion." (PMID 39911397, 2025). "CD155-TIGIT/CD96/CD226 expression was evaluated by immunohistochemistry in tumor microenvironment (TME) by pathological professionals and the associations with clinical characteristics and prognosis were investigated under a cohort study design." (PMID 41181119, 2025). "Tumor NK cells corresponded most with liver NK cells, which expressed similar inhibitory markers, such as CD96." (PMID 41208961, 2025). "Other NK receptors recognize tumor‐associated antigens (NKp30, NKp44, NKp46), cell–cell adhesion proteins (KLRG1, CD96), or genetically coupled C‐type lectin‐like ligands (NKp65, NKR‐P1)." (PMID 39748148, 2025). "Necl‐5 is often upregulated on tumor cells and increased necl‐5 expression correlates with poor prognosis, possibly through inhibition of killing by CD96+ NK cells." (PMID 39748148, 2025). "Notably, CD96 signaling dysregulation in T cells has been linked to impaired anti-tumor immunity and poor clinical outcomes, implying that targeting this pathway could enhance the therapeutic effect for this patient, providing a personalized treatment direction." (PMID 41373592, 2025). "The incoming signals from all tumor cells exhibited pattern 3, including but not limited to CD96, CEACAM, and AGRN signaling pathways." (PMID 39224598, 2024). "CD96 prevents IL-12-induced CD8+ T-cell-dependent anti-tumour effects, especially by downregulating cytokine secretion." (PMID 38893071, 2024). "TIGIT/CD226 and CD96/CD226 gene expression ratios were substantially increased in tumor-infiltrating NK cells pre-treatment, indicating a disturbed balance shifted toward NK cell inhibition." (PMID 38181797, 2024). "For instance, the expression of CD96 showed a positive correlation with M2 macrophages, indicating its potential role in modulating immune responses within the tumor microenvironment." (PMID 39655212, 2024). "The results showed a significant correlation between CHST11 and certain tumor immunostimulators (CD28, IL2RA, and TNFSF13B), tumor immunoinhibitors (CD96 and LGALS9), and MHC proteins (HLA-DRA and HLA-DMB)." (PMID 38565604, 2024). "In particular, the inhibitory checkpoint receptors TIGIT and CD96 are up-regulated during tumor progression and are able to compete with DNAM-1 for ligand binding." (PMID 37760586, 2023). "In fact, some studies have found that by blocking CD96 with antibodies improved tumor growth in mice, when combined with PD-1 blockers." (PMID 36674817, 2023). "A vast majority of studies have shown that inhibition of the immune checkpoint CD96 can be used as a therapeutic approach to enhance immune cell activity and inhibit tumor growth." (PMID 36674817, 2023). "A pivotal role in NK cell tumor immune surveillance is played by the DNAM-1/TIGIT/CD96/CD112R axis, a set of immunoglobulin immune receptors." (PMID 37760586, 2023).
tumor (continued). "In the immunohistochemical analysis of the current study, there was a clear dominance of CD96 expression in tumor-infiltrating cells." (PMID 37046787, 2023). "The current study aimed to analyze the expression of CD96 in the tumor tissue and peripheral blood of OSCC patients compared to the mucosa and blood samples of healthy volunteers on the mRNA and protein level." (PMID 37046787, 2023). "CD96 co-expression with CD226 was also significantly more frequent in cells from the blood than from the tumour (>3-fold mean difference in all subsets) and rare in tumours (Highest mean frequency of 7.3% ±1.4% in non-Treg CD4 + T cells)." (PMID 37596248, 2023). "In this brief report, we showed that CD96 inhibits human T cell anti-tumor cytotoxicity in vitro and in vivo." (PMID 36672244, 2023). "In contrast to NK cells from peripheral tumors, tumor-infiltrating NK cells had a higher proportion and intensity of CD96 on them, as well as a higher quantity of CD96+ NK cells in HCC patients." (PMID 36109471, 2023). "CD96, a possible immune checkpoint, was previously shown to suppress natural killer (NK) cell anti-tumor activity but its role in human T cells remains controversial." (PMID 36672244, 2023). "Its expression has been implicated in tumour immunosuppression, as its interaction with TIGIT or CD96-positive T lymphocytes and NK cells leads to immune exhaustion and reduced interferon-γ secretion." (PMID 37519808, 2023). "Taken together, these results indicate that CD96 enhances chemoresistance in BCSCs and promotes tumor progression." (PMID 36581470, 2023). "Previous studies have unequivocally demonstrated that CD96 plays an inhibitory role in the anti-tumor responses of murine NK cells." (PMID 36672244, 2023). "CD155 combines with CD226 to enhance T/NK cell-mediated cytotoxicity and promote anti-tumor immune response, but also interacts with TIGIT and CD96 to induce tumor immune escape and promote tumor progression." (PMID 37441080, 2023). "CD96 blocking not only increases anti‐tumor immunity but also promotes tumor cell killing by chemotherapeutic drugs." (PMID 36581470, 2023). "To investigate how CD96 regulates the anti-tumor activity of human T cells, we adopted a CRISPR/Cas9 approach to delete the CD96 gene in peripheral blood-derived T cells." (PMID 36672244, 2023). "The combination of docetaxel and a CD96 blocking antibody dramatically reduced tumor growth and enhanced apoptosis of tumor cells in high‐CD96 expressing PDXs." (PMID 36581470, 2023). "We also assessed the CD96-associated TIGIT marker, which was found to be involved in the immunosuppression of CD155 on NK cells in tumour tissue." (PMID 37760110, 2023). "Higher infiltration of CD96+ NK cells in tumor tissue showed poorer survival in pancreatic and liver cancer patients." (PMID 36750830, 2023). "Tumor cells obtained during surgical operation on tumors showing high‐CD96 or low‐CD96 expression were transplanted into NOD/SCID mice, respectively." (PMID 36581470, 2023). "In the presence of docetaxel, BCSC‐CD155 knockout largely suppressed tumor growth to the same extent as single CD96‐blocking antibody treatment." (PMID 36581470, 2023). "To investigate the role of cancer cell‐intrinsic CD96 in tumor progression and drug resistance in vivo, we established a patient‐derived tumor xenograft (PDX) model of BC in immunocompromised mice." (PMID 36581470, 2023). "Of note, a recent study in human tumor tissues revealed a correlation between CD96 expression and immune infiltration." (PMID 37629138, 2023). "In the epithelial compartment of the tumor and stroma samples, some cells with epithelial cell/tumor cell morphology also showed discrete CD96 expression." (PMID 37046787, 2023). "The findings suggest that the higher the expression of CD96 in the tumor, the higher the deterioration and recurrence rates, and the shorter patient survival times." (PMID 36674817, 2023).